ADAMTS6 (ADAM metallopeptidase with thrombospondin type 1 motif 6)
Synonyms: ADAM-TS 6; ADAM-TS6; ADAMTS-6
Tractability: Antibody: UniProt places it where antibodies can reach, with medium confidence; UniProt predicts a signal peptide or a membrane-spanning region; its Gene Ontology location is reachable by antibodies, with medium confidence.
Gene: Protein-coding gene on chromosome 5 (65,148,738 to 65,481,920, reverse strand). Ensembl gene ENSG00000049192.
Subcellular location: Secreted, extracellular space, extracellular matrix
Pathways (Reactome):
Disease: Defective B3GALTL causes PpS
Metabolism of proteins: O-glycosylation of TSR domain-containing proteins
Gene Ontology:
Molecular function: metalloendopeptidase activity; metallopeptidase activity
Biological process: extracellular matrix organization; proteolysis
Cellular component: extracellular matrix
Genetic constraint (gnomAD): Loss-of-function variants: 22 observed, 137.86 expected, observed/expected ratio (o/e) 0.16, 90% interval 0.11 to 0.23. The upper end of that interval is the gene's LOEUF score, 0.23, which puts it in group 1 of 6, group 1 being the genes least tolerant of losing a copy. Missense variants: 983 observed, 1,417.6 expected, observed/expected ratio (o/e) 0.69, 90% interval 0.66 to 0.73. Synonymous variants: 439 observed, 471.87 expected, observed/expected ratio (o/e) 0.93, 90% interval 0.86 to 1.01.
Homologues: Orthologues: chimpanzee ADAMTS6 (99% identical), macaque ADAMTS6 (99% identical), dog ADAMTS6 (98% identical), rabbit ADAMTS6 (98% identical), pig ADAMTS6 (98% identical), mouse Adamts6 (96% identical), rat Adamts6 (96% identical), guinea pig ADAMTS6 (88% identical), zebrafish adamts6 (83% identical), tropical clawed frog adamts6 (81% identical). Paralogues in human: ADAMTS10 (59% identical), ADAMTS7 (39% identical), ADAMTS18 (39% identical), ADAMTS16 (38% identical), ADAMTS12 (38% identical), ADAMTS9 (35% identical), ADAMTS20 (32% identical), ADAMTS3 (29% identical), ADAMTS19 (29% identical), ADAMTS14 (29% identical), ADAMTS2 (28% identical), ADAMTS17 (28% identical), and 13 more.
Diseases named in the same sentence as ADAMTS6 in open-access papers:
ADAMTS6 is named in the same sentence as 44 diseases in open-access papers, as found by Europe PMC text mining. Sharing a sentence is not in itself a finding about the gene and the disease. The quoted sentences say what the papers report.
breast carcinoma (9 papers, 2016 to 2025). "Artificially enhanced ADAMTS6 correlated with suppression of breast cancer cell migration, invasion and tumorigenesis and associated with disease-free survival." (PMID 36339722, 2022). "In a contrasting study, increased level of ADAMTS6 was associated with breast cancer tumor suppression in numerous breast cancer cells lines." (PMID 36339722, 2022). "Furthermore, elevated levels of ADAMTS6 mRNA associated with poor prognosis in breast cancer patients in overall survival." (PMID 36339722, 2022). "Contradictory results have been obtained in breast cancer studies, with ADAMTS6 demonstrating both pro-EMT or anti-EMT activities." (PMID 41465277, 2025). "Supporting this, nicotinamide N-methyltransferase (NNMT) decreases phosphatase PP2A methylation, which induces EMT via MEK activation in breast cancer cells and promotes migration while increasing ADAMTS6 expression in renal cancer cells." (PMID 41465277, 2025). "The findings suggest that TRPV6 activation enhances NFATc2’s transcriptional activity by modulating the phosphorylation of NFATc2IP, thereby promoting ADAMTS6 expression and facilitating metastasis in breast cancer." (PMID 40078961, 2025). "A survey of ADAMTS family members showed that ADAMTS6 expression is upregulated in breast carcinoma tissue samples with highest expression in myoepithelial cells." (PMID 36339722, 2022). "There is one study indicated that ADAMTS6 repressed breast cancer development through modulating the ERK pathway." (PMID 33063817, 2020). "Thus, the activation of NFATc2 promotes breast cancer metastasis by upregulation of ADAM metalopeptidase with thrombospondin type 1 motif 6 (ADAMTS6) expression." (PMID 40078961, 2025). "Consequently, activated NFATc2 escalates breast cancer metastasis by upregulating ADAM metallopeptidase with thrombospondin type 1 motif 6 (ADAMTS6) expression." (PMID 37892239, 2023). "Besides, some researches have demonstrated that ADAMTS6 is dysregulated in breast cancer, prolactin tumors, and colorectal cancer." (PMID 33851708, 2021). "As reported, ADAMTS6 restrained the progression of human breast cancer through ERK pathway." (PMID 33063817, 2020). "We investigated the biological function and clinical implications of ADAMTs6 in breast cancer (BC)." (PMID 27542224, 2016). "Several studies have demonstrated that it is dysregulated in some cancers such as breast cancer (BC), prolactin (PRL) tumors, and colorectal cancer; however, the precise role of ADAMTS6 in tumor development and the underlying mechanisms is unknown." (PMID 27542224, 2016). "ADAMTS6 is one of members in the ADAMTS family, playing a key role in regulating the progression of many cancers spanning several organ systems, such as breast cancer and colorectal cancer." (PMID 37214471, 2023). "In agreement, a further study showed that elevated levels of ADAMTS6 shown by RNA-seq and validated by qRT-PCR, via NFATC2 upregulation, was demonstrated in a metastasized breast cancer cell line." (PMID 36339722, 2022). "Conversely, ADAMTS6 inhibits EGFR activation without altering its expression in breast cancer cells." (PMID 41465277, 2025). "ADAMTS1 has an anti-angiogenic role, while the role of ADAMTS6 has not been defined but it is known to be dysregulated in breast carcinoma." (PMID 30546831, 2018).
Inguinal hernia (7 papers, 2015 to 2023). Protrusion of the contents of the abdominal cavity through the inguinal canal. "Two GWAS identified ADAMTS6 as a susceptible locus for inguinal hernia." (PMID 36339722, 2022). "An inguinal hernia genetic susceptibility locus near the ADAMTS6 gene has been reported, indicating that collagen deregulation could be involved in the progress of inguinal hernias." (PMID 31877874, 2019). "The association of genetic variants near ADAMTS6 supports the hypothesis that collagen dysregulation can influence the development of inguinal hernias." (PMID 26686553, 2015). "Jorgenson and colleagues previously identified 4 inguinal hernia susceptibility loci purported to result in reduced MMP activity: WT1, EFEMP1, EBF2 and ADAMTS6." (PMID 36584111, 2022). "Pathway analyses identify several genes with a strong link to collagen and/or elastin (ADAMTS6, ADAMTS16, ADAMTSL3, LOX, ELN) in the vicinity of associated loci for inguinal hernia, which substantiates an essential role of connective tissue morphology." (PMID 35680855, 2022). "We identified four novel inguinal hernia genetic susceptibility loci near the genes WT1, EFEMP1, EBF2 and ADAMTS6, and confirmed those associations in an independent cohort." (PMID 26686553, 2015). "Adamts6 expression, as determined by RNA-seq and qRT-PCR analysis, was noted in mouse connective tissue equivalent to human transversalis fascia, which when weaken or defective can lead to an inguinal hernia." (PMID 36339722, 2022). "These loci for inguinal hernia susceptibility are EFEMP1, WT1, EBF2, and ADAMTS6." (PMID 31024927, 2019).
colon cancer (3 papers, 2020 to 2025). "A subsequent study, utilizing RNA-Seq data and qRT-PCR analysis, identified ADAMTS6 as highly expressed in colon cancer tissues and cell lines and was associated with cancer progression and predicted worse prognosis in colon cancer patients." (PMID 36339722, 2022). "In our present study, we found that ADAMTS6 was highly expressed in colon cancer tissues, and high expression of ADAMTS6 was associated with worse overall survival." (PMID 33063817, 2020). "Taken together, we argued that ADAMTS6 was highly expressed in colon cancer tissues and its high expression was associated with worse overall survival in colon cancer patients for the first time." (PMID 33063817, 2020). "The association between ADAMTS6 expression and the overall survival of patients with colon cancer was explored utilizing Kaplan-Meier Plotter." (PMID 33063817, 2020). "In the present study, we first revealed that ADAMTS6 deficiency inhibited colon cancer cell proliferation, invasion and migration, whilst high expression of ADAMTS6 accelerated cell growth, invasion and migration in colon cancer cells." (PMID 33063817, 2020). "In colon cancer cells, ADAMTS6 knockdown increased E-cadherin expression and decreased N-cadherin and vimentin, while ADAMTS6 overexpression had an opposite effect." (PMID 41465277, 2025). "ADAMTS6 promotes breast and colon cancer cell invasion by inducing EMT through the AKT and NF-κB pathways." (PMID 41465277, 2025). "Consistent with this, overexpression of ADAMTS6 enhances activation of p65 through phosphorylation in colon cancer cells." (PMID 41465277, 2025). "Further qRT-PCR validation revealed that ADAMTS6 is significantly downregulated in colon cancer while significantly upregulated in rectal cancer." (PMID 36339722, 2022). "Knockdown of ADAMTS6 in a colon cancer cell line resulted in repression of colon cancer cell growth, invasion, and migration while overexpression led to the opposite." (PMID 36339722, 2022). "As the purpose of our study was to investigate the influence of ADAMTS6 on the colon cancer, therefore the following experiments were only performed using colon cancer cell lines." (PMID 33063817, 2020). "Compared to CCD-18Co cells, an obviously increase of ADAMTS6 expression was found in these 4 colon cancer cell lines." (PMID 33063817, 2020). "A CCK-8 assay was then performed to explore the effect of ADAMTS6 on the viability of normal colon cells and colon cancer cells." (PMID 33063817, 2020). "Our outcomes manifested that ADAMTS6 overexpression was concerned with worse prognosis of colon cancer patients." (PMID 33063817, 2020). "Cox proportional hazards model analysis of clinic pathologic features for overall survival of ADAMTS6 in colon cancer patients." (PMID 33063817, 2020). "Our observations will offer novel insight into the modulation of ADAMTS6 on the pathogenesis of colon cancer and provide a potential biomarker for colon cancer patients." (PMID 33063817, 2020). "To be specific, we disclosed that ADAMTS6 was highly expressed in colon cancer tissues and high expression of ADAMTS6 was related to worse prognosis in colon cancer patients." (PMID 33063817, 2020). "Together, these results provided important insights into that ADAMTS6 regulated colon cancer cell motility partially through EMT." (PMID 33063817, 2020). "Colony formation was further assayed to determine the effect of ADAMTS6 on colon cancer cell proliferation." (PMID 33063817, 2020). "The outcomes displayed that the expression of ADAMTS6 was higher in colon cancer tissues compared to that in normal samples (P <0.001)." (PMID 33063817, 2020). "In this study, we also discovered that the impacts of ADAMTS6 on colon cancer cell growth, invasion and migration was potentially modulated by EMT and the AKT/NF-κB pathway." (PMID 33063817, 2020). "We further analyzed the influences on AKT/NF-κB pathway in colon cancer cells to probe the molecular mechanisms responsible for ADAMTS6-mediated EMT promotion." (PMID 33063817, 2020).
colon cancer (continued). "Based on the data acquired from TCGA database, we revealed that ADAMTS6 was highly expressed in colon cancer tissues, and high expression of ADAMTS6 predicted worse prognosis in patients with colon cancer." (PMID 33063817, 2020). "To gain a deeper understanding on the mechanism of how ADAMTS6 affects cell growth and motility of colon cancer cells, we tested the protein levels of E-cadherin, N-cadherin, Vimentin and Snail by western blotting." (PMID 33063817, 2020). "Herein, we aimed to investigate the functions of ADAMTS6 in colon cancer and its potential mechanism." (PMID 33063817, 2020). "We then studied the expression of ADAMTS6 in 4 different colon cancer cell lines NCI-H508, Caco-2, CW-2 and HCT 116 and a normal human colon cell line CCD-18Co by qRT-PCR." (PMID 33063817, 2020). "A similar pro-EMT role of ADAMTS6 has been demonstrated in colon cancer." (PMID 41465277, 2025). "Since ADAMTS6 induces EMT in colon cancer cells via the NF-κB pathway and acts as an inducer of the TGF-β1/SMAD2/3 pathway, we investigated whether these pathways were affected by ADAMTS6 knockout." (PMID 41465277, 2025). "Further studies are warranted to fully understand the role of ADAMTS6 in colon cancer cell biology." (PMID 36339722, 2022). "Moreover, qRT-PCR demonstrated that the levels of ADAMTS6 were higher in colon cancer cell lines (NCI-H508, Caco-2, CW-2 and HCT 116) than that in normal control cell line CCD-18Co." (PMID 33063817, 2020). "Taken together, these consequences suggested the involvement of ADAMTS6 in colon cancer progression and indicated that high expression of ADAMTS6 might predict worse prognosis in colon cancer patients." (PMID 33063817, 2020). "These consequences indicated that the accelerating effect of ADAMTS6 on colon cancer cell growth, migration and invasion might be achieved by modulating EMT and AKT/NF-κB signaling pathway, offering important foundations for colon cancer treatment." (PMID 33063817, 2020). "Based on reported studies, we are the first to exhibit the roles of ADAMTS6 in colon cancer." (PMID 33063817, 2020). "Therefore, ADAMTS6 might act as a catalyst for EMT in colon cancer progression thereby enhancing colon cancer cell growth, proliferation, migration, and invasion." (PMID 36339722, 2022). "Until now, it has not been reported whether ADAMTS6 has a role in colon cancer proliferation, migration and the underlying mechanisms." (PMID 33063817, 2020). "Furthermore, we illustrated that ADAMTS6 plays a promoting role in the growth, invasion and migration of colon cancer cells, which might be realized by modulating epithelial–mesenchymal transition (EMT) and AKT/NF-κB pathway." (PMID 33063817, 2020). "However, there is few data about the mechanism of the impacts of ADAMTS6 on colon cancer." (PMID 33063817, 2020). "The univariate analysis revealed that the analyzed variables (ADAMTS6 expression, Pathologic-stage and Pathologic-TMN) were strongly related to the overall survival time of colon cancer patients." (PMID 33063817, 2020). "Therefore, ADAMTS6 might be regarded as a novel promising target for the treatment of colon cancer." (PMID 33063817, 2020). "Furthermore, ADAMTS6 mRNA expression was relatively higher expressed in NCI-H508 cells and was lower expressed in Caco-2 cells compared to other tested colon cancer cells." (PMID 33063817, 2020). "These outcomes offer a possible mechanism indicating that ADAMTS6 might act as an important contributor on EMT progression and AKT/NF-κB pathway, therefore accelerating colon cancer cell growth, migration and invasion." (PMID 33063817, 2020). "Subsequently, we conducted wound-healing assays to further examine cell migration in colon cancer cells and the results indicated that ADAMTS6 depletion significantly decreased NCI-H508 cell migration (P <0.01), whilst ADAMTS6 overexpression fortified the migratory ability of Caco-2 cells (P <0.01)." (PMID 33063817, 2020).
developmental delay (3 papers, 2019 to 2024). "Along with ARID1B, disruption of ADAMTS6 is associated with developmental delay, speech impairment, dysmorphic features and intellectual learning disability." (PMID 36339722, 2022). "Only one study has reported an association between this gene and developmental delay, suggesting that ADAMTS6 variants may affect a certain process during growth and development." (PMID 37679557, 2024). "While a few patients with developmental delay have been identified with large deletions in the ADAMTS6 locus, ARID1B is a known regulator of neural development and has previously been associated with intellectual disability." (PMID 36339722, 2022).
esophageal squamous cell carcinoma (3 papers, 2020 to 2025). Esophageal squamous cell carcinoma (ESCC) is a type of esophageal carcinoma (EC) that can affect any part of the esophagus, but is usually located in the upper or middle third. "In esophageal squamous cell carcinoma, IHC has shown co-expression of ADAMTS6 and Twist1 in patient tumors." (PMID 41465277, 2025). "The up-regulation of ADAMTS6 is a molecular marker for poor prognosis in esophageal squamous cell carcinoma." (PMID 33851708, 2021).
diabetes (2 papers, 2012 to 2024). "ADAMTS6 encodes a secreted metalloprotease, and showed the alleviating effect of insulin on diminishing ADAMTS6 levels in human cell lines, suggesting a weak link with diabetes." (PMID 39072272, 2024). "While there is also evidence linking TMEM246 and ADAMTS6 to diabetes, the association is ambiguous due to a lack of in vivo or human cell experiments." (PMID 39072272, 2024).
lung adenocarcinoma (2 papers, 2025). A carcinoma that arises from the lung and is characterized by the presence of malignant glandular epithelial cells. "A disintegrin and metalloproteinase with thrombospondin motifs 6 (ADAMTS6) is an extracellular matrix (ECM) protease that promotes the invasion of lung adenocarcinoma (LUAD) cells." (PMID 41465277, 2025).
lung carcinoma (2 papers, 2019 to 2025). "Both ADAMTS6 and ADAMTS9 gene expression is reduced in lung cancer, which may potentially be associated with the role of the genes as tumor suppressors." (PMID 39940703, 2025). "Finally, survival analysis of lung cancer patients using the kmplot.com software showed that a high expression of genes involved in ECM degradation, such as ADAM19 (p = 3.3E−5), ADAMTS6 (p = 0.00032), or MMP9 (p = 0.04), was associated with a poor prognosis." (PMID 30814494, 2019). "The greatest number of differences between normal and lung cancer samples was observed for the ADAMTS12 gene (n = 110); these changes were considerably more frequent than in ADAMTS6 and ADAMTS9 (DMRs: n = 7 and n = 10, respectively)." (PMID 39940703, 2025). "In the first stage of the analysis, the mRNA expression of the ADAMTS6, ADAMTS9, and ADAMTS12 genes was assessed in lung cancer, and the obtained results were compared with data from adjacent normal tissues." (PMID 39940703, 2025).
lymph node metastasis (2 papers, 2016 to 2021). "ADAMTS6 expression was significantly associated with the 5-year DFS of BC patients in our study, but did not correlate with patient age, tumor size, histological grade, molecular subtype, or lymph node metastasis." (PMID 27542224, 2016).
non-small cell lung carcinoma (2 papers, 2024 to 2025). A group of at least three distinct histological types of lung cancer, including non-small cell squamous cell carcinoma, adenocarcinoma, and large cell carcinoma. "Other studies have shown that ADAMTS6 may be associated with the occurrence of NSCLC (non-small-cell lung cancer) by affecting the regulation of AGR2 expression." (PMID 39940703, 2025). "Our findings indicate that the expression of the ADAMTS6 gene and the derived circRNA molecule, hsa_circ_0072676, varies considerably between the histological subtypes of non-small-cell lung cancer (NSCLC)." (PMID 38339175, 2024).
osteoarthritis (2 papers, 2022 to 2025). A noninflammatory degenerative joint disease occurring chiefly in older persons, characterized by degeneration of the articular cartilage, hypertrophy of bone at the margins and changes in the synovial membrane. "ADAMTS6 has already been implicated in osteoarthritis and it could prove fruitful to study this in an osteoarthritis mouse model, for example." (PMID 36339722, 2022). "LOF + MIS variants in ADAMTS6, SPRY2 and COLGALT2 are protective against osteoarthritis, whereas aggregation of these variants in ADAMTSL3, VIT, IL11 and THBS3 confer risk of osteoarthritis." (PMID 40205036, 2025).